DNAJC17P1 (DNAJC17 pseudogene 1)
Gene: Processed pseudogene on chromosome 2 (193,276,668 to 193,277,614, reverse strand). Ensembl gene ENSG00000235218.
Diseases named in the same sentence as DNAJC17P1 in open-access papers:
DNAJC17P1 is named in the same sentence as 1 disease in open-access papers, as found by Europe PMC text mining. Sharing a sentence is not in itself a finding about the gene and the disease. The quoted sentences say what the papers report.
infectious disease (1 paper, 2023). A disorder directly resulting from the presence and activity of a microbial, viral, or parasitic agent in humans. "The DNAJC17P1/GLULP6 gene, which is located in the intergenic region, is known to be associated with susceptibility to infectious disease as well as educational attainment." (PMID 36768488, 2023).